APC (APC regulator of Wnt signaling pathway)
Diseases named in the same sentence as APC in open-access papers (continued):
Sharing a sentence is not in itself a finding about the gene and the disease.
colorectal cancer (continued). "Finally, using DNA mass spectrometry to evaluate a panel of colorectal cancer hotspot mutations present in the ACF, we found that three APC gene mutations were positively associated with the presence of Instestinibacter sp., whereas KRAS mutations were positively correlated with Ruminococcus gnavus." (PMID 31754633, 2019). "The presence of APC mutations as an alternative to CTNNB1 mutations in some POLE‐mutant endometrial cancers is an exemplar, and there are likely to be others, such as NF1 and RB1 mutations in endometrial cancer and atypical (Q61P, K117 N, and A146T) KRAS mutations in colorectal cancer." (PMID 29604063, 2018). "In tumor suppressor genes, such as the APC gene that is inactivated in a large fraction of colorectal cancers, or Rb gene responsible for retinoblastoma, both copies must be inactivated for the resulting cell to acquire a phenotypic change that eventually may lead to cancer." (PMID 29447149, 2018). "Mutations in FBXW7 and CTNNB1 were associated with high-grade disease, the latter suggesting that activation of the Wnt pathway through CTNNB1 rather than APC mutation might predispose to poorly differentiated colorectal cancers." (PMID 30042065, 2018). "Therefore, testing for the APC AJ founder mutation in AJ families is warranted, even without a family history of colorectal cancer." (PMID 30152102, 2018). "While not all APC mutant peptides are inmmunogenic, a few qualify as vaccine candidates offering novel treatment opportunities to patients with somatic APC gene mutations to delay/treat colorectal cancer." (PMID 30256815, 2018). "Our studies revealed that the quinazoline compounds repress Wnt/β-catenin signaling without altering the level of β-catenin protein in colorectal cancer cells harboring mutations in CTNNB1 or APC, suggesting that they act on the downstream elements of the pathway." (PMID 26820295, 2016). "Given the high prevalence of APC and ARID2 mutations in other gastrointestinal tumors such as colorectal cancers and hepatocellular carcinomas instead of gastric adenocarcinomas, this finding suggests that gastric adenoma may represent a disease category distinguished from gastric adenocarcinomas." (PMID 27175599, 2016). "However, some failed to return to APC gene copy number neutrality, suggesting that duplication of the remaining allele is not always required for the development of a colorectal carcinoma." (PMID 26970738, 2016). "In this study, we present a more direct molecular link between glucose metabolism and glutamine metabolism in colorectal cancer cells: glucose deficiency induces GRP78 expression, which increases free β-catenin protein level through impairing the β-catenin-E-cadherin and β-catenin-APC complexes." (PMID 24977433, 2014). "Besides APC, colorectal cancer cells also express the paralogue APC-like (APCL)." (PMID 24722208, 2014). "Notably, c-Myc has been identified as a transcriptional target of the adenomatous polyposis coli (APC)/β-catenin/T-cell factor pathway in colorectal cancer cells, suggesting that a method of Wnt signaling function in oncogenesis is through the growth promoting activity of c-Myc." (PMID 24944693, 2014). "For colorectal cancers miRNAs are not only grouped as tumor suppressors or oncogenes, but their specific functions in CRC-associated pathways has been identified: As such, the adenomatous polyposis coli gene APC is targeted by the miR-135 family and results in a de-regulated Wnt/β-catenin pathway." (PMID 23874421, 2013).
colorectal cancer (continued). "Mutations in APC and CTNNB1 are two major factors for Wnt/β-catenin signaling activation in colorectal cancers, however recent studies indicate that the levels of Wnt/β-catenin signaling in colorectal cancer cells could be modulated on the cell surface." (PMID 22195040, 2011). "Hence, the status of PPARβ expression in colorectal cancer is controversial and whether it is regulated by the APC or the Kras oncogene yet remains to be determined." (PMID 18349831, 2008). "A proof-of-concept using whole blood from colorectal cancer patients showed high concordance between CTC markers and cells with APC abnormalities." (PMID 39858085, 2025). "In support of this, COLO-320DM (APC^p.S811*) and DLD-1 (RNF43^X659fs and RNF43^L214M), two colorectal cancer cell lines harboring Wnt pathway alterations, showed greater sensitivity to JPI-547 than to olaparib." (PMID 40959288, 2025). "For instance, p16 demonstrates hypermethylation in colorectal cancer, leukemia, and gastric cancer, as well as CDH1, APC, and CDH13 in leukemia." (PMID 39246954, 2024). "Prior studies have shown that in colorectal cancer and esophageal squamous cell carcinoma, YTHDF2 activates this pathway by targeting m6A-modified GSK3β and APC mRNAs for degradation." (PMID 38637831, 2024). "Optimal modulation of Wnt pathway activity seems critical to colorectal cancer survival, as overexpression of CTNNB1 in APC-mutant cell lines is synthetically lethal." (PMID 39324706, 2024). "Aberrant methylation of Adenomatous Polyposis Coli (APC), Dickkopf (DKK), axis inhibition protein 2 (AXIN2), and secreted frizzled-related protein (SFRP) has been identified in colorectal cancer." (PMID 36765652, 2023). "The suppressor genes APC and BRCA detected by clinicians provide a strong indication for evolution into colorectal cancer and breast cancer, respectively." (PMID 37907475, 2023). "In the current study, we employed two human colorectal cancer cell lines, HT29 and SW480; these cells carry wild-type CDH1 (E-cadherin) and CTNNB1 (β-catenin), but mutant APC, and exhibit active Wnt/β-catenin signaling." (PMID 36072467, 2022).
colorectal cancer (continued). "Moreover, I-NETs have not been reported in mice with APC mutations, and I-NETs are extremely rare in patients with familial adenomatous polyposis, in whom alleles of APC lead to intestinal polyps and colorectal cancer." (PMID 34680217, 2021). "Colorectal cancer patients with early recurrence had advanced pathological node categories, pathological tumor, node, metastasis stages, adjuvant chemotherapy treatment, a worse overall survival rate, more liver metastases and more APC mutations than those with late recurrence." (PMID 33919924, 2021). "The mRNA levels of CPEB4, APC, TRIP13, EIF2S3, EIF4A1, IFNg, PIK3CA and CTNNB1 genes expressed in colorectal cancer tissue specimens, colorectal cancer blood samples, normal colon tissues and blood samples were analysed." (PMID 33237662, 2021). "The aim of the study is to assess expression levels of CPEB4, APC, TRIP13, EIF2S3, EIF4A1, IFNg, PIK3CA and CTNNB1 genes in tumors and peripheral bloods of colorectal cancer patients in stages I–IV." (PMID 33237662, 2021). "Often, any alterations in the adenomatosis polyposis coli (APC), a tumor suppressor gene, and methylenetetrahydrofolate reductase (MTHFR) gene are related to surmise colorectal cancer significantly." (PMID 34956401, 2021). "In the colorectal cancer cell line SW480, APC IDR promotes Axin puncta formation and efficient β-catenin degradation." (PMID 33060621, 2020). "Previous studies have also shown high concordance for blood and tissue alterations, such as those in the KRAS, NRAS, APC, and BRAF genes, in colorectal cancer." (PMID 32187847, 2020). "Our results showed the negative expression of the cell cycle regulator CDKN1A and WNT signalling pathway regulator APC in a subset of the CTCs, suggesting the involvement of the canonical WNT pathway in colorectal carcinoma." (PMID 33092235, 2020). "As we showed previously and in this study, DKK2 antibody suppresses tumor growth in both APC mutant NSCLC and APC mutant colorectal cancer." (PMID 31372243, 2019). "In this study we show that the APC and KRAS mutant human colorectal cancer cell line HCT-15 induces canonical WNT signaling through YAP in a MEK dependent mechanism." (PMID 30717152, 2019). "As mutation of the tumour suppressor genes PTEN and APC are well recognized as early, if not initiating, events in the pathogenesis of endometrial and colorectal cancers, respectively, we specifically examined whether somatic variants in these genes varied according to tumour POLE mutation status." (PMID 29604063, 2018).
colorectal cancer (continued). "In fact, our results demonstrated that a higher IntegriSense accumulation was already detectable after 14 weeks of age in small intestine adenomas-bearing APC+/min mice and 2 weeks after DSS treatment in colorectal cancer-bearing APC+/min mice." (PMID 30140377, 2018). "The enhanced activity of polyamine pathways in colorectal cancer (CRC) is well known, e.g., the first rate limiting enzyme, ODC is negatively regulated by the adenomatous polyposis coli (APC) tumor-suppressor gene in colonic mucosal tissue." (PMID 29401744, 2018). "The Chinese mistletoe lectin-I CMI induced apoptosis in colorectal cancer cells CLY and HT-29 by down-regulating miR-135a&b expression and up-regulating expression of their APC (Adenomatous Polyposis Coli) target gene." (PMID 28598369, 2017). "We found that rs11954856 in the APC gene was associated with colorectal cancer and could increase the expression levels of APC, β-catenin, TCF7L1, TCF7L2 and LEF1 genes in the pathway in the CRC patients, demonstrating the involvement of APC in the pathological processes leading to CRC." (PMID 29050326, 2017). "In the human colorectal cancer (CRC) TCGA database, the subset of patients with TDG and APC expression in the lowest quartile exhibits an excess of female cases." (PMID 29163805, 2017). "Inactivation of APC (Adenomatous polyposis coli) functions and of β-catenin induces overexpression of the HDAC2 which protects colorectal cancer cells HT-29 from death." (PMID 28671573, 2017). "According to what had been founded in NCM460 and HCT116 cell lines, we suspected that in APC mutation population, ethanol was a risk factor for development of colorectal cancer, which might contribute to allowing gram-negative bacteria LPS into the blood, and activate TLR4/NF-κB signaling pathway." (PMID 26760960, 2016). "There are suggestions that aberrant Wnt/β-catenin signaling due to mutation of APC (adenomatous polyposis coli), β-catenin, or glycogen synthase Kinase 3 (GSK3) may be a common mechanism by which COX-2 expression is enhanced in gastrointestinal cancers, notably colorectal cancer." (PMID 24589238, 2014). "Tumor-specific methylation of APC, MGMT, RASSF2A and WIF1 have also been suggested as potential biomarkers for early detection of colorectal cancer." (PMID 25473433, 2014). "In colorectal cancer cells (e.g., SW480 cells), the interactions of these proteins are altered by truncation of APC." (PMID 24086117, 2013). "As an additional technical validation step, we assayed four genes (APC, MACC1, DCC, and DSC2) that have been previously established to be differentially expressed between tumor and adjacent normal tissue in colorectal cancer." (PMID 22363440, 2012). "Based upon these studies, it appears that the interaction of APC with Pol-β and other BER proteins can be an appropriate target for chemotherapeutic intervention of colorectal cancer growth." (PMID 21311763, 2011). "Furthermore, in colorectal cancer cells that have overactive β-catenin, TCF-4 is known to be growth inhibitory, as RNAi-mediated disruption of its expression facilitates β-catenin activity and cell growth in both DLD-1 cells (APC mutation) and HCT116 cells (activating β-catenin mutation)." (PMID 19924301, 2009). "A number of genes are commonly hypermethylated in colorectal cancer (CRC) including hMLH1, p16INK4a, p14ARF, RAR-β, APC, MGMT, cyclin A1, CDX1, MYOD1, COX-2 and WT-1." (PMID 19662090, 2009).
colorectal cancer (continued). "The cell lines HCT116 (colorectal cancer cell line) and HEK293 (Human embryonic kidney) both express full-length APC (314 kDa), whereas SW480 expresses a truncated APC, whose predicted size is 147 kDa, but actual running size is 152–155 kDa." (PMID 17595655, 2007). "While statins show moderate promise for colorectal cancer (CRC) chemoprevention, especially in subtypes characterized by SMAD4 positivity, APC mutations, or KRAS-driven pathways, the evidence is not yet sufficient to recommend their clinical use." (PMID 41170235, 2025). "As it is essential to consider ITH during preclinical development of anticancer therapeutics, we chose a panel of colorectal cancer PDOs spanning genetic (e.g., MSI/MSS and KRAS/BRAF /APC status), clinical stage, anatomic location, chemosensitivity, and CSC composition." (PMID 40882026, 2025). "Similarly, genetic inhibition of Wnt/β-catenin signaling (by knockout of TCF7L2) caused enhanced tyrosine phosphorylation in 2 additional models, APC-mutant HT29 and β-catenin mutant HCT116 colorectal cancer xenografts." (PMID 38488003, 2024). "In colorectal cancer, APC mutant organoids are characterized by upregulated PTK7 expression, suggesting that PTK7 targeting may be beneficial for APC mutant cases." (PMID 39474113, 2024). "Meanwhile APC shows a trend for PascalX (p-value 0.001 rank: 500 out of 18,874 protein coding genes) suggesting that APC inactivation can initiate oncogenesis earlier than KRAS activation in line with the current understanding of colorectal cancer oncogenesis." (PMID 39010058, 2024). "For PDOs derived from colorectal cancers, normal outgrowth can be prevented by the absence of Wnt ligands in the culture media, which are not needed for the proliferation of APC-mutant tumors but are necessary for wild-type APC-normal cells." (PMID 38339316, 2024). "In line with this, overexpression of PCSK9 predicts shorter survival for colorectal cancer patients with APC and KRAS mutations, but not for colorectal cancer patients with only the APC mutation." (PMID 37958351, 2023). "APC c.3920T>A; p.Ile1307Lys was observed in 18 of 126 cancer cases (14.3%) and 10 of 67 colorectal cancer cases (14.9%), compared to 4 of 57 individuals without cancer or family history of cancer (7.0%)." (PMID 37306523, 2023). "Canonical Wnt signaling is hyperactivated in many human colorectal cancers due to genetic alterations of the negative Wnt regulator APC." (PMID 35904277, 2022). "Additionally, TRABID interacts with APC tumor suppressor protein, recruits TCF target genes, and activates their transcription in colorectal cancer cells." (PMID 35874839, 2022). "On the other hand, consistent with its typical role in initiating most colorectal cancer, in MSS cancer, the mutation frequency of APC is not decreased in high-BMI patients." (PMID 36046651, 2022).